HLA-DPB1 (major histocompatibility complex, class II, DP beta 1)
Diseases named in the same sentence as HLA-DPB1 in open-access papers (continued):
Sharing a sentence is not in itself a finding about the gene and the disease.
osteosarcoma (1 paper, 2023). A usually aggressive malignant bone-forming mesenchymal neoplasm, predominantly affecting adolescents and young adults. "On the other hand, there was a slightly elevated prevalence of LOH in the HLA-DP region in osteosarcoma, with 12 (21.8%) and five (21.7%) cases in HLA-DPB1 and both HLA-DPA1-DPB1, respectively." (PMID 38318504, 2023).
periodontitis (1 paper, 2024). An acute or chronic inflammatory process that affects the tissues that surround and support the teeth. "Moreover, the upregulation of inflammatory cytokines such as CCL3 and immune response-related genes such as CD74 and HLA-DPB1 in cluster 5 suggests an enhanced immune response within the periodontal microenvironment as a hallmark of periodontitis-associated inflammation and tissue destruction." (PMID 38731950, 2024).
pneumonia (1 paper, 2023). An acute, acute and chronic, or chronic inflammation focally or diffusely affecting the lung parenchyma, caused by an infection in one or both of the lungs (by bacteria, viruses, fungi, or mycoplasma.). "HLA-DPB1*04:01 is associated with an increased risk of covid-19 double pneumonia, while HLA-DPB1*04:02 is associated with improved clinical outcomes of covid-19." (PMID 37853311, 2023).
polyarthritis (1 paper, 2012). "Positive rheumatoid factor polyarthritis has been associated with HLA-DR4 and HLA-DRB1*11; negative rheumatoid factor polyarthritis has been demonstrated to be associated with HLA-DRB1*08 and HLA-DPB1*03." (PMID 23133455, 2012).
respiratory failure (1 paper, 2022). The significant impairment of gas exchange within the lungs resulting in hypoxia, hypercarbia, or both, to the extent that organ tissue perfusion is severely compromised. "Reduced expression of HLA-DPB1 described herein is fully compatible with the decreased expression of HLA-DR on the cell membranes of circulating monocytes of patients with severe respiratory failure by SARS-CoV-2." (PMID 35042868, 2022).
skin reaction (1 paper, 2024). "Here, we report the first evidence of the HLA-DPB1*05:01 allele in association with the occurrence of pustular skin reaction in AOID patients, representing a novel biomarker to distinguish pustular skin reactions in AOID from PP patients." (PMID 38540337, 2024).
testicular cancer (1 paper, 2023). A primary or metastatic malignant neoplasm that affects the testis. "Except for HLA‐DPB1, the remaining seven genes have not been studied in testicular cancer." (PMID 37543714, 2023).
thrombosis (1 paper, 2023). "A previous report showed potential correlations between HLA-DPB1 and HLA-DPA1 and thrombosis and ANCA-associated vasculitide (AAV)-associated thrombus formation." (PMID 37539039, 2023).
thyroid (1 paper, 2025). "Integration with conventional DEG signatures revealed a functionally cohesive module, with C1QA/B/C, FLT1, TEK, PDGFRB, SPP1, and HLA-DPB1 emerging as central regulators of thyroid irAEs." (PMID 41221294, 2025).
tumor (68 papers, 2009 to 2025). "Overexpression of HLA-DPB2 promotes tumor immune infiltration by regulating HLA-DPB1, which is associated with a high survival rate in breast cancer." (PMID 36564433, 2022). "To ascertain the relationship between HLA-DPB1/HLA-DPB1 and the various immune infiltrating cells, we further evaluated the associations between HLA-DPB1/HLA-DPB1 and biomarkers of tumor-infiltrating immune cells in BC and its subtype using data from the TIMER database." (PMID 32903535, 2020). "HLA-DPB1 TAM was enriched for HLA-DPB1, involved in enhancing tumoral antigen presentation and recruiting CD8 + T cells to facilitate antitumor immune responses, thus, characterized as M1 tumor-associated macrophages (M1 TAM)." (PMID 39334513, 2024). "Cluster Fib_5 prominently expressed MHC-II genes (HLA-DQA1, HLA-DQA2, HLA-DQB1, HLA-DRB5, HLA-DRB1, HLA-DRA, HLA-DPA1, and HLA-DPB1), indicating their role as antigen-presenting cells with tumor-suppressing effects." (PMID 37533434, 2023). "A previous study that performed immunohistochemical analysis with anti-CD74 (HLA class II histocompatibility antigen gamma chain) and anti-HLA-DPB1 in TNBC tumor specimens revealed that all five examined specimens had CD74 protein expression in tumor cells." (PMID 28817603, 2017). "Furthermore, KRAS-G12V-specific TCR-engineered CD4+ T cells have shown excellent anti-tumor effectiveness in vitro and in xenograft models, identifying the neoantigens derived from HLA-DPB1*03:01 and DPB1*14:01." (PMID 40075634, 2025). "TIMELESS expression in LUAD tumor tissues was significantly negatively correlated with neutrophil biomarkers, dendritic cell biomarkers (HLA-DPB1, HLA-DQB1, HLA-DRA, HLA-DPA1, CD1C) and an immunophenoscore that predicted outcomes associated with the use of immune checkpoint inhibitors." (PMID 38261568, 2024). "In this study, we isolated and identified the HLA-DPB1*03:01-restricted human TILs from patient’s tumor tissue that recognize natural processed and presented epitopes in KRASG12V mutants, and cloned the TCRs to construct KRASG12V-reactive TCR-engineered CD4+ T cells." (PMID 37287989, 2023). "In addition, we observed that several MHC family members, such as HLA-DRA, HLA-DRB1, HLA-DPA1 and HLA-DPB1, were highly expressed in response tumour samples." (PMID 36581917, 2022). "This risk modulation may be mediated by alteration of antigen recognition and tumor clearance, due to variation at the binding pocket of the HLA-DPB1 protein (amino acid positions 84–87)." (PMID 34440582, 2021). "We obtained results on the correlation between TPPP3 expression and marker genes of tumor infiltration-associated immune cells, including CD8+T cells (CD8A and CD8B), B cell (CD19 and CD79a), and Myeloid dendritic cell (HLA-DPB1, HLA-DQB1, HLA-DRA, HLA-DPA1, CD1C, NRP1, and ITGAX)." (PMID 33083464, 2020). "Furthermore, a number of interferon (IFN) response genes (BST2, CD74, HLA-DMA, HLA-DPB1, HLA-DQB1, HLA-DRA, HLA-DRB1, and IRF8) were upregulated in C10 compared to the other clusters, whereas genes associated with tumor suppression and apoptosis (TFF1 and TFF2) were downregulated." (PMID 37370788, 2023). "Moreover, the communication between tumor and immune cells was more widespread in the HER2neg group, especially in immune response-related crosstalk between tumor cells and myeloid cells (which was primarily comprised of macrophages), such as “HLA-DPB1–TNFSF13B” and “TNFRSF1A–GRN”." (PMID 36998014, 2023). "Therefore, we supposed that the HLA-DPB2/HLA-DPB1 axis might exert its roles in BC by involving an immune response in the tumor microenvironment." (PMID 32903535, 2020). "Thus, the mechanism determining how the HLA-DPB1 variation affects the risk of EGFR mutation-positive LADC should be further investigated, particularly with respect to the possibility that it affects immune responses against EGFR-positive tumour cells." (PMID 27501781, 2016).
tumor (continued). "TIMELESS expression was significantly negatively correlated with neutrophil biomarkers (CEACAM8) and dendritic cell biomarkers (HLA-DPB1, HLA-DQB1, HLA-DRA, HLA-DPA1, CD1C) in TCGA LUAD tumor tissues." (PMID 38261568, 2024). "Elevated expression of MHC-II molecule (HLA-DPB1) was evident post-transfection, underscoring the correlation between HPV infection and MHC-II expression in tumor cells." (PMID 39105803, 2024). "The top 100 genes found to be co-expressed with CD74 were examined using GEPIA2.0, finding that the top five genes (HLA-DMA, HLA-DPA1, HLA-DPB1, HLA-DRA, and HLA-DRB1) were highly correlated with CD74 in most tumor types." (PMID 38582956, 2024). "Compared to adjacent normal tissues in naïve samples, HLA-DPB1 TAM was decreased, while MT1G TAM increased significantly in tumor tissues (P < 0.01, Mann-Whitney U test)." (PMID 39334513, 2024). "Consistently, the IHC staining of CD19 and MHC class II proteins showed that the number of HLA‐DPB1+ and CD19+ cells were significantly decreased in tumor comparing with adjacent regions (p = .0004, paired Student's t‐test)." (PMID 34185431, 2021). "Based on literature reports and our findings, we speculate that the HLA-DPB2/HLA-DPB1 axis may convert immunologically “cold” tumors to “hot” tumors and thus exert an anticancer role in BC by recruiting T lymphocytes and NK cells into the tumor microenvironment." (PMID 32903535, 2020). "Meanwhile, HLA-DPA1, HLA-DQA1, HLA-DPB1 and HLA-DMB belong to MHC class II, one of the most important components in tumor-immune interactions." (PMID 33066530, 2020). "HLA-DPB1 protein expression was noted in two of five TNBC tumors, with weak-to-moderate cytoplasmic and membranous staining in 20% and 40% of tumor cells, respectively." (PMID 28817603, 2017). "Additionally, ENHO was positively co-expressed with MHC class II presentation genes (including HLA-DMA, HLA-DOA, HLA-DPA1, HLA-DPB1, and HLA-DRB1), supporting its role in promoting anti-tumor immunity." (PMID 40647442, 2025). "It is worth noting that the interaction between HLA‐II molecules (such as HLA‐DRA, HLA‐DRB1, HLA‐DRB5, HLA‐DQB1, HLA‐DPB1, HLA‐DPA1, HLA‐DMB and HLA‐DMA) and the receptor CD4 was exclusively detected in the cell communication between malignant cells from single‐primary tumours and Tregs." (PMID 39601163, 2024). "However, the expressions of IGKC, IGLC1, ITGB2, CTSS, HLA‐DPB1, and RSAD2 were elevated in tumor tissue and they served as protective factors." (PMID 37543714, 2023). "However, Mono-FCGR3A in high tumor infiltration group expressed lower levels of MHC molecules, inflammatory cytokines and chemokines (HLA-DRB1/HLA-DPB1, TNF, IL1B, CCL3 and CCL4), which meant the sub-cluster was less involved in immune responses." (PMID 36532059, 2022). "We adjusted these results based on tumor purity, revealing strong and significant correlations between CD96 and CD8+ T cell markers (CD8A), general T cell markers (CD3D, CD3E, CD2), DC markers (HLA-DPB1, HLA-DRA, HLA-DPA1) in LGG." (PMID 33680972, 2021). "The earlier discussed findings indicate that HLA-DPB2 and HLA-DPB1 take part in the tumor suppression processes of BC and that overexpression of HLA-DPB2 may predict a favorable prognosis by regulating the parent gene HLA-DPB1 expression." (PMID 32903535, 2020). "However, cDCs in the PI3K/mTORi+PD‐1i‐treated tumours upregulated expression of genes related to antigen presentation via major histocompatibility complex class II (MHC II) (HLA‐DRB1, HLA‐DQB1, HLA‐DPB1, HLA‐DQB2, CD74) compared with cDCs in tumours treated with PD‐1i, PI3K/mTORi‐ or vehicle." (PMID 38711203, 2024). "At present, tumor-related immunomodulators have become an important method for BC treatment, and in this study, we found that DHCR7 expression is significantly correlated with the immunoinhibitor, immunostimulators, and MHC molecules, including CD96, CD48, and HLA-DPB1." (PMID 38526324, 2024).
tumor (continued). "However, CD8 T cells only recognized HLA-DPB1*03:01-transfected tumor cells upon expression of TCR DP03chim but not TCR DP03WT." (PMID 32443793, 2020). "Based on the gene markers and the high expression of HLA-DPB1, S100A6, HLA-DRA, and other genes related to antigen presentation in GSVA, SC-C1 and SC-C3 cells were mainly enriched in hematopoiesis, suggesting that SC-C3 cells may be related to tumor vascular proliferation." (PMID 36304995, 2022). "Notably, HLA-II expression in tumor cells was not uniform across the genes examined, with significantly higher HLA-DRB1 than HLA-DQA1, HLA-DQB1, and HLA-DPB1 (p < 0.0001, Kruskal–Wallis)." (PMID 35831288, 2022).
cancer (22 papers, 2015 to 2026). A tumor composed of atypical neoplastic, often pleomorphic cells that invade other tissues. "The strongest association with a young age at cancer diagnosis in LSVH was conferred by the presence of the HLA-DPB1*04:02 class II allele." (PMID 38929796, 2024). "TCR transgenic CD4+ T cells targeting HLA-DPB1*04:01 restricted melanoma-associated antigen A3 (MAGE-A3) also showed efficiency in various cancer types." (PMID 35269735, 2022). "When validated in a larger cohort, these high-risk HLA-DPB1 alleles could be factored into cancer risk prediction models for personalized cancer screening in LSVH." (PMID 38929796, 2024). "The involvement of HLA-DPB1 alleles in the age at cancer diagnosis may highlight the potential role of HLA class II in the immune response against cancer development in LSVH." (PMID 38929796, 2024). "Herein, the HLA DPB1 gene promoter was found to be significantly hypomethylated in cancer tissue (63%) in comparison to healthy oral mucosa tissue (0%)." (PMID 37175405, 2023). "HLA class II molecules like HLA-DPB1, HLA-DRA, HLA-DRB1, and HLA-DQB1 are associated with antigen processing and presentation to CD4+ T cells, and the down-regulation of these genes is related to poor prognosis of cancers." (PMID 36417424, 2022). "One of the earliest reports involved selection and expansion of clonal autologous CD4+ T cells from a melanoma patient recognizing an epitope from a shared cancer-testis antigen (NY-ESO-1) presented in the context of HLA-DPB1*0401; infusion of these cells led to a long-term complete response." (PMID 34910940, 2021). "This patient shares the same HLA-DPB1 and HLA-DQB1 molecules with FM3 cancer cells (both positive for DPB1 04:01, DQB1 06:03 and 06:02, respectively)." (PMID 40333248, 2025). "We noticed that some MHC class II genes (HLA-DMA, HLA-DPA1, HLA-DPB1, HLA-DRA, HLA-DRB1) were significantly down-regulated in cancer cells with relatively poor differentiation states compared with those with better differentiation states for 5/6 mGC patients." (PMID 37347037, 2023). "Cell therapy with retrovirally transduced CD4+ T cells expressing a TCR specific-for-another-cancer-testis antigen, MAGE-A3, presented by HLA-DPB1*0401 also led to partial and complete response across several tumor types." (PMID 34910940, 2021). "As for MHC molecules, we found the MHC class II molecules including HLA-DPA1, HLA-DPB1, HLA-DRA, HLA-DRB1, HLA-DQA1, HLA-DQB1 showed a stronger relation with PD-1 than other MHC molecules in some cancer types." (PMID 30607140, 2018).
infection (17 papers, 2008 to 2025). The state of being infected such as from the introduction of a foreign agent such as serum, vaccine, antigenic substance or organism. "Finally, we compared the mRNA vaccine-induced populations of antigen-specific CD4+ T cells in the blood with antigen-specific CD4+ T cells obtained from a cohort of HLA-DPB1*04+ individuals following infection with SARS-CoV-2." (PMID 37790414, 2023). "Finally, we incorporate analysis of antigen-specific CD4+ T cells found in blood from a cohort of HLA-DPB1*04+ human subjects following primary infection with SARS-CoV-2 and compare these responses to spike-specific memory CD4+ T cells found after vaccination." (PMID 37790414, 2023). "A recent study reported that a variety of HLA-DRB1 alleles/haplotypes were associated with altered Ct infection risk, and differential rate of clearance in a cohort of Columbian women; HLA-DPB1 alleles were not examined." (PMID 36248887, 2022). "The role of alleles encoded by major histocompatibility loci (MHC) have been examined in a number of previous studies and results indicating weak, multi-allele associations between the HLA-DPB1 locus and BCP-ALL suggested a role for immunosusceptibility and possibly infection." (PMID 24959916, 2014). "We found expression of HLA-DPB1, a MHC class II gene, in CD14+ monocytes was inversely correlated with severity of infection, whereas expression of alarmins (e.g., S100A9) in CD14+ monocytes was positively correlated with severity." (PMID 33765435, 2021).
gastrointestinal tumor (1 paper, 2024). "We further found NOTCH3 levels in gastrointestinal tumor to correlate with markers of Dendritic cell(HLA-DPB1, HLA-DRA, HLA-DPA1, BDCA-4), Tfh(T-bet, STAT4, STAT1, TNF-α), Treg cells (FOXP3, CCR8, STAT5B, TGFβ) and T cell exhaustion (PD-1, CTLA4, LAG3, TIM-3)." (PMID 38906903, 2024).
inflammatory myopathies (1 paper, 2017). "The last candidate from the top 10 SNP association list is HLA-DPB1, an immune response gene that has been linked to rheumatoid and inflammatory myopathies." (PMID 28077804, 2017).
kidney disease (1 paper, 2021). "Our findings indicate that a high expression of different co-DEGs was correlated with a low glomerular filtration rate in kidney disease samples (IL10RA, HLA-DPA1, r = −0.490, p < 0.001; IRF8, HLA-DRA, r = −0.500, p < 0.001; HLA-DPB1, r = −0.510, p < 0.001; HLA-DMA, r = −0.480, p < 0.001)." (PMID 34692653, 2021).
HLA-DPB1 also shares sentences with these, for which no sentence is quoted: systemic lupus erythematosus (5 papers); aplastic anemia (3); glioma (3); neuroblastoma (3); adenocarcinoma (2); chronic graft versus host disease (2); colorectal cancer (2); dilated cardiomyopathy (2); hematologic malignancies (2); Hypertension (2); immune deficiencies (2); inflammatory bowel disease (2); Japanese encephalitis (2); lung fibrosis (2); mental disorder (2); ovarian carcinoma (2); primary biliary cholangitis (2); pulmonary hypertension (2); Sjögren syndrome (2); ulcerative colitis (2); viral myocarditis (2); acute lymphoblastic leukemia (1); allergic asthma (1); ankylosing spondylitis (1); Arrhythmia (1); atherosclerosis (1); atopic dermatitis (1); autoimmune hepatitis (1); autoimmune PAP (1); Behcet Syndrome (1).
A further 71 diseases each share a sentence with HLA-DPB1 in 1 paper.